CYP26B1 (cytochrome P450 family 26 subfamily B member 1)
Diseases named in the same sentence as CYP26B1 in open-access papers (continued):
Sharing a sentence is not in itself a finding about the gene and the disease.
oral squamous cell carcinoma (3 papers, 2014 to 2025). "Among them, CYP26B1 is a risk factor for esophageal squamous cell carcinoma and increases the risk of oral squamous cell carcinoma 35, 36, but its association with BLCA was unclear." (PMID 40535799, 2025). "According to Chen and colleagues was documented that oral squamous cell carcinoma exhibited a notable upregulation of CYP26B1." (PMID 38870259, 2024).
Anxiety (2 papers, 2022 to 2024). Intense feelings of nervousness, tension, or panic often arise in response to interpersonal stresses. "A recent study showed that the knockdown of CYP26B1 in the nucleus accumbens shell increases depression-related behavior while decreasing anxiety-like behavior, implicating the function of CYP26B1 in the adult CNS." (PMID 37639183, 2024). "Most interestingly, knockdown Cyp26b1 in the nucleus accumbens shell decreased anxiety-like behavior." (PMID 35237186, 2022).
bladder cancer (2 papers, 2024 to 2025). "In summary, this study not only expands our understanding of the molecular mechanisms underlying bladder cancer but also emphasizes the therapeutic potential of targeting CYP26B1 in RA metabolism." (PMID 40535799, 2025). "This study aims to fill this gap by examining the impact of CYP26B1 on bladder cancer progression and its association with the immune microenvironment." (PMID 40535799, 2025). "In this study, we found that CYP26B1 is significantly associated with the poor prognosis of bladder cancer and have used cell phenotypic experiments to confirm that over-expression of CYP26B1 can promote the proliferation and migration abilities of tumor cells." (PMID 40535799, 2025). "Specifically, we utilized a subcutaneous xenograft model in nude mice to investigate the effect of CYP26B1 on bladder cancer growth." (PMID 40535799, 2025). "Future research should focus on the potential for RA-based therapies in combination with immune checkpoint inhibitors and explore the role of CYP26B1 in various stages of bladder cancer development." (PMID 40535799, 2025). "We provide compelling evidence that CYP26B1 is a key player in bladder cancer progression, offering a novel perspective on RA metabolism in this malignancy." (PMID 40535799, 2025). "The key enzyme of RA metabolism, CYP26B1, can be used as a potential therapeutic target for bladder cancer, and its expression can effectively promote the stemness of bladder cancer." (PMID 40535799, 2025). "The CCK-8 assay confirmed that CYP26B1 overexpression can enhance the proliferation ability of bladder cancer cells." (PMID 40535799, 2025). "Using a combination of bioinformatics analysis and experimental validation, we explore how CYP26B1 influences both tumor growth and the immune landscape within bladder cancer." (PMID 40535799, 2025). "In vitro experiments were undertaken to explore the potential role of CYP26B1 in bladder cancer (BLCA), utilizing MIBC (5637) and NMIBC (RT4) cell lines." (PMID 40535799, 2025). "This study provides novel insights into the role of CYP26B1 in bladder cancer, particularly its impact on both tumor progression and immune cell infiltration, which has not been thoroughly explored in this context." (PMID 40535799, 2025). "Recent studies have highlighted CYP26B1 as a potential therapeutic target in cancers such as prostate and liver cancer, but its significance in bladder cancer has remained underexplored." (PMID 40535799, 2025). "We found that TNFRSF12A, IL1R1, ELN and CYP26B1 were overexpressed in bladder cancer cell lines, while NR1H3 and ITIH4 were downregulated." (PMID 38216619, 2024). "The expression and potential therapeutic targeting of CYP26B1 in bladder cancer could therefore offer a new avenue for treatment, similar to its role in other malignancies." (PMID 40535799, 2025).
Brachycephaly (2 papers, 2013 to 2023). An abnormality of skull shape characterized by a decreased anterior-posterior diameter. "Microdeletions affecting CYP26B1 and EXOC6B were identified in two individuals with brachycephaly, facial asymmetry, abnormal ears, mild joint contractures (elbow/knee) and neurological features (autism spectrum disorder, hyperactivity, and aggressive behaviour)." (PMID 37755482, 2023).
craniorachischisis (2 papers, 2020 to 2023). Craniorachischisis is the most severe form of neural tube defect in which both the brain and spinal cord remain open to varying degrees. "In the present study, our data indicated that in addition to PCP genes, variants in retinoic acid related gene CYP26B1 and chromatin modification genes are associated with craniorachischisis prevalence." (PMID 32650820, 2020). "Interestingly, the degradation enzyme for retinoic acid encoded by the CYP26B1 gene harbors significant number of PDRVs in craniorachischisis cases (2/19 in craniorachischisis vs. 0/225 in all controls; P = 0.007)." (PMID 32650820, 2020). "For instance, variants in the CYP26B1 gene, occurring concurrently with other variants in neural tube-related genes such as CELSR3 and REST, were hypothesized to be associated with the craniorachischisis phenotype." (PMID 37424722, 2023).
esophageal squamous cell carcinoma (2 papers, 2021 to 2025). Esophageal squamous cell carcinoma (ESCC) is a type of esophageal carcinoma (EC) that can affect any part of the esophagus, but is usually located in the upper or middle third. "In this regard, a recent GWAS revealed an association of CYP26B1 with esophageal squamous cell carcinoma risk." (PMID 33802237, 2021). "A genome-wide association study (GWAS) on the Chinese population identified CYP26B1 as a candidate gene for esophageal squamous cell carcinoma risk." (PMID 33802237, 2021).
inflammatory bowel disease (2 papers, 2013). A spectrum of small and large bowel inflammatory diseases of unknown etiology. "Allele frequencies of the polymorphism rs2241057 in the CYP26B1 gene in patients with inflammatory bowel disease vs. healthy controls." (PMID 23977348, 2013). "Genotype frequencies of the polymorphism rs2241057 in the CYP26B1 gene in patients with inflammatory bowel disease vs. healthy controls." (PMID 23977348, 2013). "Thus, Cyp26b1 may serve as a novel therapeutic target to treat inflammatory bowel disease." (PMID 23991089, 2013).
male infertility (2 papers, 2013 to 2021). The inability of the male to effect fertilization of an ovum after a specified period of unprotected intercourse. "Considering the function of CYP26B1 in biogenesis and postnatal growth, we speculate that the genetic variation may affect the capacity of CYP26B1 enzyme, then the meiotic program of germ cell, which might tightly associates with male infertility." (PMID 23320086, 2013).
sarcopenia (2 papers, 2024 to 2026). Progressive decline in muscle mass due to aging which results in decreased functional capacity of muscles. "CIBERSORT analysis showed the relationship between these genes and immune cell subsets, while Mendelian randomization (MR) analysis confirmed the causal relationship between the expression of CYP26B1 gene and the risk of sarcopenia." (PMID 41836872, 2026). "Then, ROC analysis was conducted to assess the diagnostic value of the target genes in sarcopenia, and the AUC values of CERS3, ADH1B, CYP26B1, and NNMT were greater than 0.7." (PMID 38838088, 2024).
acne vulgaris (1 paper, 2022). "Tretinoin (DB00755) targeting CYP26B1 is used to treat fine wrinkles, acne vulgaris, and certain types of promyelocytic leukemia." (PMID 35875800, 2022).
Allergy (1 paper, 2025). An allergy is an immune response or reaction to substances that are usually not harmful. "Among sex- and allergy-independent migraine-associated genes, CYP26B1 and CORIN deserve particular attention." (PMID 40350427, 2025). "This was in part due to the replication criterion, partly due to allergy-correction, as evidenced by the large number of additional pathways and the significantly replicated CYP26B1 gene in the allergy-uncorrected analysis." (PMID 40350427, 2025). "CORIN and CYP26B1 remained LEGs with largest mean log2 FC, with the latter reaching FDR-significance at both time points in allergy-uncorrected analysis." (PMID 40350427, 2025).
bladder tumor (1 paper, 2025). "This is supported by the significant inhibition of bladder tumor cell growth when CYP26B1 expression is inhibited." (PMID 40535799, 2025). "The results confirmed that overexpression of CYP26B1 promoted bladder tumor growth." (PMID 40535799, 2025).
cervical cancer (1 paper, 2024). A primary or metastatic malignant neoplasm involving the cervix. "According to Wang and colleagues was discovered that CYP26B1 had a significant presence in the retinoic acid metabolic process and the retinol metabolism pathway, exerting a crucial influence on the advancement of cervical cancer across various age brackets." (PMID 38870259, 2024).
Cirrhosis (1 paper, 2025). A chronic disorder of the liver in which liver tissue becomes scarred and is partially replaced by regenerative nodules and fibrotic tissue resulting in loss of liver function. "Among all, the top 5 hub genes identified for NAFLD vs. control were CXCL9, NOS2, SERPINE1, FABP4, and LPL, whereas AKR1D1, UGT2B17, CYP26B1, LIPC, and DGAT2 were identified as the top 5 hub genes for the NAFLD vs. cirrhosis group." (PMID 40365443, 2025). "Additionally, the top 5 biological functional hub genes in NAFLD vs. control (CXCL9, NOS2, SERPINE1, FABP4, and LPL) and NAFLD vs. cirrhosis (AKR1D1, UGT2B17, CYP26B1, LIPC, and DGAT2) groups were identified through PPI analysis among lipid, immune, and metabolism dysregulated genes." (PMID 40365443, 2025).
colon adenocarcinoma (1 paper, 2025). "Moreover, CYP26B1 expression was inversely correlated with HRD (homologous recombination deficiency) scores in BLCA and BRCA, while in other cancer types like BRCA and colon adenocarcinoma, CYP26B1 expression was positively correlated with MSI (microsatellite instability) scores." (PMID 40535799, 2025).
colon cancer (1 paper, 2023). "Further, CYP26B1 is associated with poor prognosis in colon cancer." (PMID 37185128, 2023). "We analyzed gene expression of Cyp26a1, Cyp26b1 and Cyp26c1 in N-MFs and CAFs isolated colon cancer patients." (PMID 37185128, 2023).
Crohn disease (1 paper, 2013). A gastrointestinal disorder characterized by chronic inflammation involving all layers of the intestinal wall, noncaseating granulomas affecting the intestinal wall and regional lymph nodes, and transmural fibrosis. "Allele frequencies of the polymorphism rs2241057 in the CYP26B1 gene for patients with Crohn’s disease versus healthy controls, displayed for sub phenotypes and clinical features." (PMID 23977348, 2013). "Genotype frequencies of the polymorphism rs2241057 in the CYP26B1 gene for patients with Crohn’s disease and healthy controls, displayed for sub phenotypes and clinical features." (PMID 23977348, 2013). "Cytochrome P450 26 B1 (CYP26B1) is involved in the degradation of retinoic acid and the polymorphism rs2241057 has an elevated catabolic function of retinoic acid, why we hypothesized that the rs2241057 polymorphism may affect the risk of Crohn’s disease (CD) and Ulcerative Colitis (UC)." (PMID 23977348, 2013).
dermatitis (1 paper, 2013). An inflammatory process affecting the skin. "Accordingly, we found that expression of genes encoding RA degradation enzymes, cytochrome P450 26a1 (Cyp26a1; eight-fold induction) and Cyp26b1 (two-fold increase) was increased in allergen-induced dermatitis." (PMID 23977003, 2013).
diabetes (1 paper, 2023). "However, our data show that Tbx1 expression in mouse embryos did not alter under maternal diabetes with or without PHZ treatment, which are in line with the findings of unchanged Cyp26b1 and Cyp26c1 expressions in diabetic pregnancy." (PMID 37616226, 2023).
diabetic retinopathy (1 paper, 2022). "For example, genes such as Aldh1a3, Cyp26b1 and Acaa2, without reference regarding anti-diabetic retinopathy function, would be the candidates for our future exploration." (PMID 36557283, 2022).
Ewing sarcoma (1 paper, 2015). A small round cell tumor that lacks morphologic, immunohistochemical, and electron microscopic evidence of neuroectodermal differentiation. "OX40L transgenic Ewing sarcoma cells showed preserved expression of Ewing sarcoma-associated (anti)gens including lipase member I, cyclin D1 (CCND1), cytochrome P450 family member 26B1 (CYP26B1), and the Ewing sarcoma breakpoint region 1-friend leukemia virus integration 1 (EWSR1-FLI1) oncogene." (PMID 26579494, 2015).
gastric cancer (1 paper, 2023). A primary or metastatic malignant neoplasm involving the stomach. "Moreover, CYP26B1 and DHRS3 up-regulation indicates that ATRA causes significant effects on the metabolism of endogenous vitamin-A in gastric-cancer cells." (PMID 37951921, 2023). "A final and significant outcome of our study is the identification of a restricted number of genes which are up-regulated (IRF1, CTSS, PSMB10, CYP26B1, DHRS3 and TINAGL1) and down-regulated (AHNAK2) by ATRA in all the retinoid-sensitive gastric-cancer cell-lines considered." (PMID 37951921, 2023).
growth disorders (1 paper, 2021). "Interestingly, multiple sox family members (sox5, sox6, sox8, and sox18) were significantly dysregulated in shox-deficient pectoral fins together with other genes (nppa, nppc, cdkn1a, cdkn1ca, cyp26b1, and cy26c1), highlighting an important role for these genes in shox-related growth disorders." (PMID 34122528, 2021).
hepatocellular carcinoma (1 paper, 2024). A malignant tumor that arises from hepatocytes. "For hepatocellular carcinoma (HCC), we performed a tumor classification using a 4-gene signature (CYP26B1, MCM10, SPINK4, and TRIM54) derived from differentially expressed genes (DEGs) associated with ubiquitination." (PMID 38870259, 2024).
Hydrocephalus (1 paper, 2023). Hydrocephalus is an active distension of the ventricular system of the brain resulting from inadequate passage of CSF from its point of production within the cerebral ventricles to its point of absorption into the systemic circulation. "In family 2, a stillborn fetus presented a lethal phenotype with spina bifida occulta, hydrocephalus, poor skeletal mineralization, synostosis, limb defects, and a synonymous homozygous variant in CYP26B1: c.1083C > A." (PMID 37755482, 2023).
infarction (1 paper, 2013). A localised pathological necrosis of tissue resulting from obstruction of the blood supply usually by a thrombus, an embolus, or vascular torsion. "Interestingly, the expression of CYP26B1 was limited to the infarction area and was essentially missing in the viable heart muscle of both groups." (PMID 23554885, 2013).
Infertility (1 paper, 2013). "Eight single nucleotide polymorphisms (SNPs) in CYP26B1, NANOS1 and STRA8 genes were determined by TaqMan allelic discrimination assay in 719 idiopathic infertile men and 383 healthy controls." (PMID 23320086, 2013).
juvenile idiopathic arthritis (1 paper, 2018). Juvenile idiopathic arthritis (JIA) is the term used to describe a group of inflammatory articular disorders of unknown cause that begin before the age of 16 and last over 6 weeks. "Expression differences of other transcripts, like TGS1 and CYP26B1 (that are differentially expressed in tuberculosis and juvenile idiopathic arthritis, respectively) could be related to neutrophil responses to intravascular perturbations during IA." (PMID 30593281, 2018).
metastatic colorectal cancer (1 paper, 2014). "CYP26A1, CYP26B1 and LRAT all showed immunoreactivity in both normal colonic epithelium and primary and metastatic colorectal cancer and in each case immunostaining was localised to the cytoplasm of cells." (PMID 24608339, 2014).
migraine (1 paper, 2025). "Difference in CYP26B1 was identified as key alteration in migraine." (PMID 40350427, 2025). "Both 1) the downregulated CYP26B1-levels, which are reliant on the substrate, all-trans retinoic acid (atRA) in the heart and vasculature and 2) the lack of CYP26B1 SNPs associated with migraine even on a nominal level, indicated a marker role for CYP26B1 for reduced atRA levels in MO." (PMID 40350427, 2025).
oral disorders (1 paper, 2015). "This is the first study to indicate that the mRNA expression of CYP26 families (CYP26A1 and CYP26B1) and their SNP variants play a novel role in the occurrence or developmental mechanism of malignant oral disorders." (PMID 25839051, 2015).
osteosarcoma (1 paper, 2020). A usually aggressive malignant bone-forming mesenchymal neoplasm, predominantly affecting adolescents and young adults. "Three of highly expressed genes (DDX10, FOXA2, and HEY1) were correlated with poor prognosis, while three of lowly expressed genes (CYP26B1, GP1BB, and IFI44) showed the opposite trend in patients with osteosarcoma." (PMID 32284759, 2020). "High expression of CYP26B1, GP1BB, and IFI44 in osteosarcoma patients was correlated with good prognosis, while high expression of DDX10 and FOXA2 in osteosarcoma patients was associated with poor prognosis." (PMID 32284759, 2020).
spina bifida cystica (1 paper, 2020). A congenital abnormality in which the spinal cord and meninges protrude through a defect in the spinal column. "Three cases of lumbar spina bifida cystica revealed one PDRV in the retinoid metabolism gene CYP26B1 (1/3 vs. 0/225, P = 0.017)." (PMID 32650820, 2020).
viral infection (1 paper, 2013). "Gene ontology classes of the predicted cellular targets of HPV16-miR-H1-1 suggest important roles in host cell interactions of HPV 16, such as the cell cycle process (CUL3, CYP26B1, MAP3K11, PBRM1, SMC1A), especially the M phase (CYP26B1, PBRM1, SMC1A), which is important for viral infection." (PMID 23936163, 2013).